ENSG00000303956 (novel transcript, antisense to EFCC1)
Gene: Long non-coding RNA gene on chromosome 3 (129,031,608 to 129,056,954, reverse strand). Ensembl gene ENSG00000303956.
Gene Ontology:
Biological process: SRP-dependent cotranslational protein targeting to membrane, signal sequence recognition
Cellular component: signal recognition particle, endoplasmic reticulum targeting